C5 (complement C5)
Diseases named in the same sentence as C5 in open-access papers (continued):
Sharing a sentence is not in itself a finding about the gene and the disease.
proliferative glomerulonephritis (1 paper, 2020). A constellation of renal disorders characterized by an increase number of cells in the glomerulus; these disorders generally present with nephrotic syndrome, and generally progress to end stage renal failure over a matter of weeks to years, depending on the etiology. "One pathway is C5 independent and causes injury to the glomerular capillary wall, characterized by proteinuria and podocyte foot process effacement, while the other pathway is C5 dependent and responsible for proliferative glomerulonephritis and kidney dysfunction." (PMID 32447506, 2020).
relapsing fever (1 paper, 2015). Relapsing fever is an infection caused by bacteria of the genus Borrelia, excluding those responsible for Lyme disease belonging to the Borrelia burgdorferi complex. "For example, a salivary protein, OmCI, from the Ornithodoros moubata tick, the vector of human relapsing fever caused by Borrelia duttoni, was shown to specifically bind and inhibit C5, thereby preventing activation of the terminal complement pathway." (PMID 25679788, 2015).
retinoblastoma (1 paper, 2021). A malignant tumor that originates in the nuclear layer of the retina. "In contrast, MYCN was highly expressed in c5 (retinoblastoma cells) a gene played crucial roles in tumour cell proliferation that was consistent with previous study." (PMID 34815392, 2021).
sarcoidosis (1 paper, 2025). Sarcoidosis is a multisystemic disorder of unknown cause characterized by the formation of immune granulomas in involved organs. "Complement C5 (P01031) and C8a (P07357) are actively synthesized in alveolar macrophages in sarcoidosis." (PMID 41279897, 2025).
SARS-CoV infection (1 paper, 2021). "Also in murine models it has been previously shown that, during infection with different human coronaviruses, depletion or blockage of complement component 3 (C3) in SARS-CoV infection and complement component 5 (C5) in MERS-CoV infection resulted in milder disease severity." (PMID 34194438, 2021).
sickle cell disease (1 paper, 2018). Sickle cell anemias are chronic hemolytic diseases that may induce three types of acute accidents: severe anemia, severe bacterial infections, and ischemic vasoocclusive accidents (VOA) caused by sickle-shaped red blood cells obstructing small blood vessels and capillaries. "The effectiveness of C5 inhibition in PNH and aHUS opens up a gateway for testing this strategy in a large panoply of other diseases, as diverse as graft rejection, sickle cell disease or even cancer, where complement contributes to pathogenesis." (PMID 30555486, 2018).
ST-elevated myocardial infarction (1 paper, 2015). "Consistent with the protective effects seen in experimental studies interfering with C5 function, treatment with anti-C5 antibody (Pexelizumab) resulted in significantly reduced mortality in ST-elevated myocardial infarction (STEMI) patients." (PMID 25784879, 2015).
thalassemia (1 paper, 2026). An inherited blood disorder characterized by a decreased synthesis of one of the polypeptide chains that form hemoglobin. "When aHUS is combined with thalassemia, large amounts of hemoglobin are released from fragmented erythrocytes, leading to amplification of the complement cascade and resulting in a "two-hit" mechanism that may affect the efficacy of C5 inhibitors." (PMID 42125085, 2026).
Thromboembolism (1 paper, 2019). The formation of a blood clot inside a blood vessel that subsequently travels through the blood stream from the site where it formed to another location in the body, generally leading to vascular occlusion at the distant site. "Thanks to the first therapeutic C5 inhibitor eculizumab we have controlled the most debilitating symptoms of PNH, and prevented the most devastating life-threatening complications, such as thromboembolism." (PMID 31258525, 2019).
urticaria (1 paper, 2023). A vascular reaction of the skin characterized by erythema and wheal formation due to localized increase of vascular permeability. "The activation of coagulation factors and complement systems C3 and C5 have been studied on development of chronic spontaneous urticaria and it was suggested that coagulation factors and C5/C5a induce histamine release from mast cells." (PMID 37762646, 2023).
ZIKV infection (1 paper, 2020). "IPA also predicted many cytokines, including IL-15, IL-27, IL-32, C5, IL-18, and EB13, were significantly up-regulated by ZIKV infection in HSerC." (PMID 32511241, 2020).
infection (113 papers, 2008 to 2025). The state of being infected such as from the introduction of a foreign agent such as serum, vaccine, antigenic substance or organism. "Herein, we are presenting a series of three children diagnosed with infection-associated HUS treated with complement C5-inhibitor ECZ." (PMID 40065282, 2025). "We retrospectively reviewed three infection-associated HUS cases treated with complement C5-inhibitor ECZ in our institute (Institute of Pediatrics, University of Debrecen, Hungary)." (PMID 40065282, 2025). "C5 is a component of the complement system and essential for host defense against Mtb, as C5-deficient mice exhibit increased susceptibility to infection." (PMID 40487315, 2025). "The gene encoding complement component 5 (C5) displayed high expression in piglets with an ineffectively treated infection." (PMID 40995220, 2025). "We report on three children (median age: 2 years, range: 2–10 years) diagnosed with infection-associated HUS treated with complement C5-inhibitor ECZ." (PMID 40065282, 2025). "In contrast, inhibiting downstream complement components, such as C5, causes an impaired response to infection in sera from vaccinated patients." (PMID 37441479, 2023). "We, therefore, used our CEACAM1-humanized mouse model in combination with deficiencies in C3 (C3−/-), C5 (C5−/-), C3aR1 (C3ar1-/-) C5aR1 (C5ar1−/-) or C5aR2 (C5ar2−/-) to monitor Nme nasal colonization following intranasal infection with 105 CFU." (PMID 31274379, 2019). "The inflammatory cytokine TNFα which is induced by infection (e.g. with pathogenic Salmonella) induces expression of all complement related genes except C5, C8GH and CR2." (PMID 31888466, 2019). "Overall, infection with Neisseria meningitidis appears to be the most common infectious complication of complement deficiency, and this is by far the most common infection in those with deficiencies in terminal complement proteins (i.e. C5 – C9)." (PMID 22551888, 2012). "However, blocking C5 exposes patients to a high risk of infection with encapsulated bacteria, i.e. Neisseria meningitidis, due to impaired MAC generation, which can be largely mitigated by vaccination and antibiotic prophylaxis." (PMID 40370446, 2025). "Infection-related AEs constituted 11,957 cases, predominantly linked to C5 inhibitors." (PMID 40860872, 2025). "Furthermore, data have shown that AAV patients treated with C5 blockade (eculizumab) are at a higher risk of infection, especially with Neisseria meningitidis, despite the use of vaccination protocols and prophylactic antimicrobials." (PMID 39407748, 2024). "Neutrophils play a major protective role against dissemination of C. neoformans, and C5aR signaling is required for infection-induced neutrophil recruitment to the brain as suggested by data obtained in a murine infection model using C5 deficiency and inhibitory anti-C5aR antibodies." (PMID 34408631, 2021). "C5 deficiency is protective against infection-induced seizures." (PMID 34408631, 2021). "The decrease of certain complement components, as for instance C5 deficiency, is associated with higher levels of circulating inflammatory cytokines in response to infection, suggesting that SLE may aggravate systemic inflammation during infection." (PMID 23675429, 2013). "Our previous studies had suggested that C5-deficiency might predispose mice to cardiac dysfunction since they suffer from depressed cardiac metabolism within 24 h of infection with C. albicans blastospores." (PMID 21829669, 2011). "From the perspective of infection risks caused by encapsulated bacteria, in vitro results with Hib, meningococci and pneumococci indicate potential advantages of AP inhibitors over C3 and C5 inhibitors, in particular, when treatment is combined with prior vaccination of patients." (PMID 36578495, 2022).
infection (continued). "In the present study, we employed a different mouse strain (A/J; C5 deficient; C5−/−) and evaluated the systemic levels of pro- and anti-inflammatory cytokines during Leptospira infection in the blood, liver, lung, and kidney on the third and sixth days after infection." (PMID 31687410, 2019). "The difference in clearance of bacteria from the site of infection to the locally draining inguinal lymph node observed in both wildtype and C5 deficient mice was diminished in C3-/-/C5-/- mice, suggesting that cleavage of C3 may be responsible for this phenotype." (PMID 28806402, 2017). "In view of age-associated reduction in immune function and the effect of eculizumab on the suppression of the terminal complement pathway (i.e., C5 and subsequent components), one concern is that treatment with eculizumab may elevate the risk of infection in elderly patients." (PMID 24455465, 2014). "C5 inhibitors accounted for the majority of infection-related reports, but this proportion is almost certainly over-estimated because C5 inhibitors are used not only for PNH but also for several other indications." (PMID 40860872, 2025). "Typically, cleavage of C3, C4, and C5 is critical for phagocyte recruitment to the site of infection." (PMID 39813225, 2025). "Among infection-related AEs, advanced age (>75 years) and C5 inhibitor use emerged as significant predictors of fatal outcomes." (PMID 40860872, 2025). "After GCRV infection, grass carp spleens demonstrated impaired complement and coagulation cascades and reduced transcription of key genes such as the C3, C5, and complement factor 7 genes, indicating GCRV’s ability to hinder these cascades in grass carp." (PMID 38666826, 2024). "During infection, local and plasma levels of C5a/C5a des-Arg are increased during the late steps of complement activation through the cleavage of C5 by C5 convertase assembled on the surface of microbes." (PMID 39771599, 2024). "Using our murine model of S. epidermidis catheter infection we quantified levels of the complement components C1q, Factor B, MASP2, C3, and C5 over the course of infection along with bacterial burdens." (PMID 38881889, 2024). "In particular, the non-linear target-mediated elimination of eculizumab can vary over time, due to variations in the amount of available C5 (e.g. due to infection)." (PMID 35238929, 2023). "In this study, we demonstrated that TYLCV encodes a C5 protein, which is a virulence factor and enhances the pathogenicity of PVX in N. benthamiana, and is important for the TYLCV infection." (PMID 37676365, 2022). "It is noteworthy that, with the sole exception of Abs to C5, immunization by the three vaccine regimens induced responses that were equal to or stronger than those induced by infection." (PMID 35173151, 2022). "For complement components, complement C1s, C5, and C8 were significantly increased under the JDm10 infection." (PMID 35893682, 2022). "Here we also showed that a PVX-based vector expressing C5 can induce severe mosaic symptoms and elevated ROS during infection, strongly suggesting that C5 has a role in viral pathogenicity and induction of host defense responses." (PMID 37676365, 2022). "Our study shows how S. chrysophrii infection changes the abundance of several complement proteins (factor H, factor B, factor I, C1q, C3, C4, C5, C6, C7, C8), inducing an inhibition of the alternative pathway as the infection intensity increases." (PMID 36088326, 2022). "The significant reduction of the bands of C5α chain demonstrated that C5 was largely cleaved by the lysates collected at 36 h and 44 h post-infection." (PMID 35087765, 2021). "Day-to-day fluctuations in C5 concentrations are possible as a result of complement-activating events such as infection, surgery, and pregnancy; the eculizumab dosing regimen helps prevent C5 concentration increases translating into clinical relapse." (PMID 34803867, 2021).
infection (continued). "Western blot analysis revealed distinct bands corresponding to the C5-derived ~38-kDa fragment in the wild-type infection group after incubation for 5 and 15 min." (PMID 35087765, 2021). "HeLa229 cells infected with C. trachomatis L2 (MOI=1) with or without addition of 100 U/mL Penicillin G. Lysates collected at 44 h post-infection were co-incubated with purified C5 (400 nM) for 120 min." (PMID 35087765, 2021). "Two patients had C3 and/or C5 nephritic factors and 5 patients had infection-related complement consumption." (PMID 32972440, 2020). "In an additional group of animals, the plasma, brain, and liver were collected on PND5 or PND9 after infection to evaluate cytokine and chemokine profiles, C5a levels and C5 signaling." (PMID 32373108, 2020). "C5 and C9 participate in the complement activation pathway, and the complement system is a main line of defense against infection." (PMID 32365127, 2020). "We also blocked complement activation at the level of C5, which abrogated the effect of mAb 2C7 in clearing infection in mice." (PMID 31216278, 2019). "A/J C5+/+ mice had higher levels of liver IL-10, IL-1β, IL-12p40, and IL-12p70 and kidney IL-1β, IL-12p40, and IL-12p70 on the sixth day of infection when compared to A/J C5−/− mice." (PMID 31687410, 2019). "A/J C5+/+ mice had higher levels of liver IL-10, IL-1β, IL-12p40, and IL-12p70 and kidney IL-1β, IL-12p40, and IL-12p70 on the sixth day of infection than A/J C5−/−." (PMID 31687410, 2019). "Since the Complement System is important to eliminate leptospires in vivo, we investigated if Complement C5 in A/J mice would modulate the cytokine production during infection by Leptospira interrogans serovar Kennewicki type Pomona Fromm (LPF)." (PMID 31687410, 2019). "C5 plays several critical roles in the host response to infection, including target lysis and phagocyte recruitment." (PMID 31484737, 2019). "In our model of LPF infection, both A/J C5+/+ and A/J C5−/− mice showed leukocyte infiltration on the third day and mitotic cells on the sixth day of infection." (PMID 31687410, 2019). "The C5 protein involved in the recruitment of cellular component of the immune system at the site of infection showed five unique substitutions." (PMID 30283495, 2018). "The concentrations of C3a, C3b, C5 and C5a were, however, also increased in the late phase of infection." (PMID 30094629, 2018). "To validate a clear role for the C3-ase activity of ScpA in vivo, utilizing the same soft-tissue infection model, we compared the pathogenesis of GAS-M1 and GAS-M1ΔscpA in complement deficient (C3-/-/C5-/-) mice." (PMID 28806402, 2017). "The relevance of complement activation for the immune response against C. albicans is demonstrated by infection of C3- and C5-knockout mice, which show increased mortality as a consequence of impaired anti-Candida response and infection-driven immunopathology." (PMID 28133459, 2016). "Previous investigators have evaluated S. aureus foot-pad infection in a NOD diabetic mouse model, but the mice were C5-deficient limiting the ability to evaluate complement-mediated effects." (PMID 25610878, 2014). "This study demonstrates for the first time a strong and complex influence of complement effector functions, downstream of C3 and upstream of C5, on the outcome of an infection with intracellular bacteria, such as C. psittaci." (PMID 23189195, 2012). "Upon establishment of P. intermedia and P. gingivalis at the site of infection, higher concentrations of proteases lead to complement inhibition by degradation of C3, C4 and C5." (PMID 22514678, 2012). "Infection of N. benthamiana with the PVX construct expressing the c5 gene of Cotton leaf curl Kokhran virus (CLCuKoV; PVX-Ko-c5) showed very mild leaf curl and light green mosaics across the leaf lamina, in systemic leaves at approx. 8 dpi." (PMID 21592402, 2011).